GLS (glutaminase)
Diseases named in the same sentence as GLS in open-access papers (continued):
Sharing a sentence is not in itself a finding about the gene and the disease.
tumor (continued). "When comparing the levels of glutaminase mRNA expression in biological subtypes, there was a significantly lower level of GLS in luminal B compared with luminal A tumours (p < 0.001)." (PMID 34439127, 2021). "Glutamine, in high concentration in the tumor, is imported into tumor cells and converted into glutamate by glutaminase (GLS)." (PMID 34885023, 2021). "Previous reports have shown that high proliferative tumours such as TNBC and luminal B have higher glutamine metabolism and show increased activity of glutaminase compared to low proliferating tumours." (PMID 34439127, 2021). "Examination of ex vivo tumor tissues showed that GLS activity was also significantly higher in NHAALT tumors relative to NHATERT and tumor-free normal brain." (PMID 33397920, 2021). "With respect to the luminal subtypes, both luminal A (low proliferative) and B (high proliferative) tumours showed a weak positive correlation between GLS mRNA and protein expression with GLUD1 and SLC38A2 (p < 0.01)." (PMID 34439127, 2021). "We observed that dual inhibition of glutaminase and signal transduction pathways lead to synergistic anti-proliferative activity in vitro and enhanced anti-tumor activity in vivo." (PMID 34731180, 2021). "To further explore our findings in a clinically relevant setting, we analyzed the hLcn-2-dependent target genes SLC7A11, GCLM, and GLS at mRNA level in either tumor tissue or adjacent healthy tissue of 32 patients diagnosed with clear cell RCC (ccRCC)." (PMID 34069743, 2021). "Previous studies also found that GLS silencing led to the increased sensitivity of tumor cells to chemotherapy drugs." (PMID 34354052, 2021). "Second, many neoplasms increase their glutaminolysis e.g., by oncogene (myc)-driven glutaminase (GLS) overexpression." (PMID 34041023, 2021). "MYC signalling also increases the dependency on glutamine metabolism and uptake in basal-like tumours, characterized by high glutaminase (GLS) and low GS levels." (PMID 34572926, 2021). "This indicates that hBCATc can function in conjunction with glutaminase to enhance glutamate flux to tumour cells and fuel cell growth through the TCA cycle." (PMID 33367952, 2021). "IDH1 mutant tumor cells rely on glutaminase (GLS) activity to maintain α-KG homeostasis, making GLS inhibition a good therapeutic target." (PMID 34067729, 2021). "Promisingly, small molecule GLS inhibitors have been shown to exhibit anti-proliferative activity and reduce tumour burden across a variety of tumours, including lymphoma, breast, pancreatic, non–small cell lung and renal cancers." (PMID 34541580, 2021). "The results showed that EZH2 was highly expressed in the outer layers of tumor tissues, while GLS was highly expressed in the inner layers." (PMID 34671029, 2021). "High GLS and GLS2 mRNA were associated with lower tumour grade (p = 0.017, p = 0.026, respectively)." (PMID 34439127, 2021). "Upregulated expression of SLC7A11 (10/14), SLC1A5 (7/14), SLC7A5 (6/14), and SLC3A2 (5/14) was observed in most of the tumor tissues; however, GLS in LUSC, KIRC, and KICH and GLS2 in KIRC and LIHC, were significantly downregulated." (PMID 34573287, 2021). "Inhibitors of glutaminase or transaminase have shown the therapeutic efficacy in multiple MYC-driven tumour models, and a representative glutaminase inhibitor, CB-839, is currently under clinical trials for patient treatment." (PMID 34195095, 2021). "Other groups have reported that mTOR inhibition increases GLS expression, thus increasing tumor dependency on glutamine as a potential resistance mechanism to mTOR inhibition." (PMID 34731180, 2021). "Applying RNA sequencing analysis in renal CAKI1 tumor cells to explore highly upregulated molecular signatures in response to hLcn-2, we identified a cluster of genes (SLC7A11, GCLM, GLS), which are implicated in regulating ferroptosis." (PMID 34069743, 2021).
tumor (continued). "The residual tumours following treatment with glutaminase inhibitor displayed metabolic changes including increased glycolysis and glycogenesis, suggestive of adaptive metabolic reprogramming that compromises therapy efficacy." (PMID 32450839, 2020). "Specifically, KISS1R regulates the expression of the transcription factor c-Myc and glutaminase that are necessary for glutamine catabolism and therefore drives processes such as nucleotide synthesis required for tumor growth." (PMID 32034133, 2020). "In order to translate our in vitro data to clinics we examined for the first time the expression of GLS-1 in various Pheo/PGL tumor tissues with known genetic background by immunohistochemistry." (PMID 32150977, 2020). "Combined inhibition of mTOR kinase and GLS resulted in synergistic tumour cell death and growth inhibition in mice bearing GBM." (PMID 33092283, 2020). "PDK and glutaminase inhibition deserve to be studied in vivo in order to have reliable data about their impact on tumor angiogenesis." (PMID 33076309, 2020). "This study highlights the potential influence that both circulating and tumour-derived pyruvate can have on glutaminase inhibitor efficacy." (PMID 32450839, 2020). "Pyruvate carboxylase increased activity has been reported as a potential metabolic mechanism for tumor growth in situations where GLS activity is challenged However, a decrease in lactate levels with metformin or combination treatment was observed via NMR." (PMID 32158544, 2020). "In vitro studies have shown that metformin has an inhibitory effect on glutaminase (GLS) activity in tumor cells." (PMID 33664666, 2020). "Similar observations in reducing tumor growth were observed in combining glycolysis inhibitors (Glutor or lonidamine) with either DON or the glutaminase inhibitor CB-839." (PMID 33251492, 2020). "Treatment of melanoma cells with the GLS inhibitor BPTES enhanced the anti-tumour activity of BRAF inhibition by suppressing the switch toward glutamine metabolism and OXPHOS." (PMID 33092283, 2020). "These new discoveries highlight the potential influence that circulating and tumour-derived pyruvate and other microenvironmental features can have on glutaminase inhibitor efficacy." (PMID 32450839, 2020). "Further, combination-treated OS cells showed a reduction in cellular mitochondrial respiration, while NMR confirmed the pharmacodynamic effects of glutaminase inhibition in tumor tissues." (PMID 32158544, 2020). "Treatment of TIGAR-overexpressing ESCC cell xenografts and patient-derived tumor xenografts in mice with combination of glutaminase inhibitor and chemotherapeutic agents achieves significant more efficacy than chemotherapy alone." (PMID 32206103, 2020). "GLS overexpression has been observed in different tumor cells, and these enzymes are found to function in the metabolic reprogramming of glutamine addiction in cancer." (PMID 32943735, 2020). "GLS1 loss in TNBC cell lines leads to dysregulated glutaminolysis, impairing tumor growth in vitro and in vivo, whereas GLS silencing has minimal effects on metabolic phenotype or growth in luminal cell lines." (PMID 32296646, 2020). "Here, we found that tumor-bearing caused an increase in the plasma glutamine level and tumor expression of SLC1A5, SLC7A5, and that glutaminase was further elevated in obese mice." (PMID 32121098, 2020). "Which of these mechanisms occur and are relevant in the response of human tumours to glutaminase inhibition is yet to be definitively established." (PMID 32450839, 2020). "Several GLS inhibitors have been developed and have shown tumor-suppressive activities in preclinical models, although such agents have been found to lack therapeutic effects in certain instances." (PMID 32184390, 2020). "Our findings suggest that GLS inhibition suppresses proliferation and viability of tumour-derived UPS, HT1080, and SK-LMS-1 cells in vitro." (PMID 31980651, 2020).
tumor (continued). "Altogether, the response to GLS inhibition remains highly dependent on cell of origin and surrounding tissue to dictate tumour metabolism and sometimes the adaptive mechanisms that mitigate effects of metabolic drugs, like CB-839." (PMID 31980651, 2020). "Inhibitors of glutaminase or transaminase have shown the therapeutic efficacy in multiple MYC-driven tumor models, and a representative glutaminase inhibitor, CB-839, is currently under clinical trials for patient treatment." (PMID 32651356, 2020). "The intervention in glutamate metabolism by glutaminase inhibitors was shown to impact the glutathione level and thus, reduce the antioxidative tumor capacity." (PMID 32605263, 2020). "Overexpression of GLS allows for increased glutamine metabolism, thereby providing a means for the tumor cells to replenish the citric acid cycle and produce molecules required for anabolic growth." (PMID 32937954, 2020). "Further, inhibitors such as bis-2-(5-phenylacetamido-1,2,4-thiadiazol-2-yl)ethyl sulfide (BPTES), CB-839, and compound 968 represent a unique class of drugs developed to target tumor-specific isoforms of glutaminase (GLS)." (PMID 31652923, 2019). "Compound 968 is another glutaminase inhibitor with potent anti-tumour properties: in fact, compound 968 activates apoptosis, and decreases the invasiveness and resistance of MDA-MB-231 cells to the chemotherapeutic drug doxorubicin." (PMID 31052256, 2019). "Since Wnt/β-catenin signaling pathway plays a key role in the regulation of tumor progression and is aberrantly activated in PCa, we then examined the role of GLS in Wnt/β-catenin signaling." (PMID 31196962, 2019). "Conversely, the expression of GLS2, the mitochondrial isoform of glutaminase, inversely correlates with tumor stage, tumor size, and prognosis in HCC." (PMID 31027222, 2019). "Oncogenes and tumor suppressors can control Gln metabolism through regulating the expression and/or activation of glutaminase (GLS), the key rate-limiting enzyme for glutaminolysis." (PMID 30899002, 2019). "The most clinically relevant glutaminase inhibitor, CB-839, has shown pre-clinical activity in a variety of mouse models and is currently in clinical trials for several tumor types." (PMID 31096630, 2019). "Based on accumulating evidence, ASNS, GOT2, and GLS, as well as asparagine, substantially contribute to tumor growth and metastasis." (PMID 30858360, 2019). "Recently drugs targeting glutaminase activity has been successfully used in preclinical trials to impede the invasiveness of tumor cells, thus counteracting EMT." (PMID 31849832, 2019). "In this model, combination treatment with a glutaminase inhibitor induced synthetic lethality in tumor cells." (PMID 31824848, 2019). "Blocking glutaminase activity by CB-839 prevented pro-tumor activity in triple-negative breast cancer." (PMID 31666638, 2019). "GLS and GLS2 are respectively indirect and direct downstream targets of c-Myc35 and were significantly overexpressed in FH-deficient tumor specimens." (PMID 31804603, 2019). "GLS-encoded glutaminase promotes tumorigenesis, while GLS2-encoded glutaminase displays tumor-suppressive properties." (PMID 30669455, 2019). "Unlike asparagine, aspartate and arginine, cystine was found to increase tumor cells’ sensitivity to glutaminase inhibition, when supplemented above physiological levels in tissue-culturing medium." (PMID 31212591, 2019). "The correct balance of these metabolic activities is crucial for T cell function, as exemplified by infiltrating lymphocytes in a tumor microenvironment in which ROS, glutaminase and arginase contribute to lower the activation potential of immune cells." (PMID 31841528, 2019). "Tumor growth was further reduced when in vivo cells were treated with CB-839, a GLS inhibitor, suggesting that loss of AGC1 can synergize with GLS inhibitors." (PMID 31881713, 2019).
tumor (continued). "Glutaminase (GLS), which converts glutamine into glutamate, plays a vital role in up-regulating cell metabolism for tumor cell growth." (PMID 31196962, 2019). "This export of mitochondrial aspartate into the cytosol is mediated by the mitochondrial aspartate-glutamate carrier 1 (AGC1), and genetic inhibition of AGC1 compromises xenograft tumor growth when a glutaminase inhibitor is used." (PMID 31212591, 2019). "The three proteasome inhibitors which downregulated MYC expression in HLRCC tumor cells, also decreased the expression of GLS and GLS2." (PMID 31804603, 2019). "Recently, GLS inhibitors, such as CB-839, an orally available, potent, and specific inhibitor of GLS, have shown anti-tumor efficacy." (PMID 28748451, 2018). "We found that the expression levels of GAC and glutaminase activity were higher in most tumor tissues than in normal lung tissues." (PMID 29515166, 2018). "The same experiments using treatment with metformin and/or glutaminase inhibitor were performed with the tumor-organoid model of human CRC." (PMID 29323154, 2018). "High 18F-glutamine uptake was related to increased sodium-dependent neutral amino acid transporter type 2 (SLA1A5) expression and by upregulated glutaminase (GLS) in several tumor models." (PMID 29629339, 2018). "The c-Myc-induced miR-23a inhibition enhanced the glutaminase isoform GLS expression, and initiated the metabolic reprograming of tumor cells towards a glutamate-addictive phenotype." (PMID 30577536, 2018). "More generally, tumor cells overexpressing MYC are highly sensitive to GLS inhibition as they mainly rely on glutamine oxidation to replenish the TCA cycle, even in hypoxic conditions." (PMID 30564554, 2018). "This suggests that GLS inhibition has the dual functions of inhibiting tumor cell growth and immune evasion." (PMID 30619766, 2018). "Glutamine consumption is characteristic for many tumours with increased glutaminase (GLS) expression." (PMID 30574020, 2018). "Estimation of changes in pool size with 18F-Gln provides the ability to infer tumor glutaminolysis in vivo, suggesting its use as a biomarker to select patients for glutaminase therapy." (PMID 30042161, 2018). "We report for the first time, a strong correlation between the NF1 status of tumor cells and increased sensitivity to glutamine deprivation and glutaminase inhibition." (PMID 29212209, 2017). "Tight regulation of glutaminase activity and glutamate metabolism are vital features of both stem cell function and tumor survival." (PMID 29052507, 2017). "Tumor cell environment can also influence dependence on glutaminase for anaplerosis and proliferation." (PMID 28826492, 2017). "Our findings in vitro were recapitulated in vivo as inducible knockdown of GLS in tumor xenografts resulted in a similar change in metabolite levels, suppressed tumor growth or tumor regression." (PMID 28950000, 2017). "Although unexpected based on the phenotypes observed upon GLS knockdown with shRNA, the results do agree with the limited single agent anti-tumor activity of CB-839 reported in the literature." (PMID 28950000, 2017). "We thank Calithera Biosciences for use of CB-839, LC-MS/MS based measurement of CB-839 tumour and plasma levels and GLS inhibition assays." (PMID 28671190, 2017). "The report also showed that genetic inhibition of human GLS mRNA expression in subcutaneous tumor mouse model would also lead to tumor growth suppression." (PMID 28750681, 2017). "The conversion of glutamine to glutamate was catalyzed by glutaminase, which was overexpressed in both solid tumors and many tumor cell lines." (PMID 28744216, 2017). "Consistent with our in vitro results, doxycycline induced GLS knockdown led to profound tumor growth inhibition in vivo." (PMID 28950000, 2017).
tumor (continued). "On the other hand, GBM cells have been demonstrated to withstand mTOR inhibition by activating glutamine metabolism via glutaminase (GLS) and combined mTOR and GLS inhibition results in synergistic tumor growth inhibition in a GBM preclinical setting." (PMID 29179732, 2017). "The enzyme mRNA expression was evaluated by qRT-PCR analysis, confirming the decrease of GLS expression in tumor cell lines compared to HPDE, and the increase of mRNA levels of both GDH1 and GDH2 in PDAC cell lines compared to non-PDAC and control human cells." (PMID 29221133, 2017). "Another link between oncogenic activation and tumour cell metabolism was determined when a study established that c-Myc increased glutaminase expression by suppressing miR-23a/b." (PMID 27825361, 2016). "Glutaminase C (GAC), a splice variant of kidney-type glutaminase, has been demonstrated to be the major form of GLS in tumor cells." (PMID 26575584, 2016). "Increased expression of glutaminase upregulated the glutaminolysis and produced more ATP and glutathione, resulting in protective roles in tumor cells from reactive oxygen species damage." (PMID 27612201, 2016). "As the key and limit enzyme in catalyzing glutaminolysis, glutaminase is becoming an attractive target for tumor therapy and regarded as the new research direction." (PMID 27612201, 2016). "Small-molecule inhibitors such as BPTES and CB-839, which target the allosteric site of glutaminase with high specificity, demonstrate immense promise as anti-tumor drugs." (PMID 27462863, 2016). "Inhibition of glutaminase reduced glutathione antioxidant capacity and increased apoptosis of tumor cells." (PMID 27612201, 2016). "Potent allosteric inhibitors of glutaminase and tumor-specific IDH2 mutants are currently being tested in clinical trials." (PMID 27756303, 2016). "Glutaminolysis, which triggers tumor growth was reportedly inhibited by glutaminase (GLS) inhibitor such as Bis-2-[5-phenylacetamido-1,2,4-thiadiazol-2-yl] ethyl sulphide (BPTES) or siRNA." (PMID 26437434, 2015). "Pharmacological inhibition of GLS is being investigated as a potential means of therapy for a number of different tumor types." (PMID 25621173, 2015). "For example, 6-diazo-5-oxo-1-norleucine (L-DON), targets glutaminase on its active site to inhibit tumor growth." (PMID 26139106, 2015). "Restriction of glutamine metabolism through depriving glutamine, blocking glutamine transporters or inhibiting GLS activity have been proved to be effective in inhibiting tumor cell growth by inducing apoptosis and/or autophagy both in vitro and in vivo." (PMID 26402672, 2015). "The presence of LGA and/or KGA, together with GAC (Glutaminase C) form has also been reported in different tumour cells." (PMID 25329718, 2014). "Glutaminase has emerged as one of several enzymes utilized by tumors to enable Gln use as a key nutrient for some tumor cells." (PMID 25502225, 2014). "HER2 type showed the highest tumor and stromal ATP synthase expression (P = 0.027 and P < 0.001, respectively) and stromal glutaminase expression (P = 0.001), whereas luminal A type showed the lowest expression of those markers." (PMID 24020991, 2013). "We identified the expression of a mitochondrial metabolism-related protein such as ATP synthase and glutaminase in the tumor and stroma in the present study." (PMID 24020991, 2013). "The Gln-ind cells overexpressed cyclooxygenase-2, an indicator of tumor aggressiveness, and they were able to adjust their glutaminase level to suit glutamine availability." (PMID 22570721, 2012). "In order to obtain energy and the essential precursors for the synthesis of macromolecules, tumor mitochondria adapt by overexpressing glutaminase facilitating the use of glutamate as a fuel." (PMID 20824065, 2010).